FAAP100 (FA core complex associated protein 100)
Description:
Plays a role in Fanconi anemia-associated DNA damage response network. Regulates FANCD2 monoubiquitination and the stability of the FA core complex. Induces chromosomal instability as well as hypersensitivity to DNA cross-linking agents, when repressed.
Synonyms: C17orf70; FLJ22175; FANCX
Tractability: PROTAC: ubiquitination databases record sites on it; its protein half-life has been measured.
Gene: Protein-coding gene on chromosome 17 (81,539,885 to 81,553,961, reverse strand). Ensembl gene ENSG00000185504.
Subcellular location: Nucleus
Subcellular location (Human Protein Atlas): Nucleoplasm; Cytosol
Pathways (Reactome):
DNA Repair: Fanconi Anemia Pathway
Immune System: PKR-mediated signaling
Gene Ontology:
Molecular function: protein binding
Biological process: interstrand cross-link repair
Cellular component: chromatin; Fanconi anaemia nuclear complex; nucleoplasm; nucleus; cytosol
Genetic constraint (gnomAD): Loss-of-function variants: 46 observed, 54.66 expected, observed/expected ratio (o/e) 0.84, 90% interval 0.66 to 1.08. The synonymous counts are far from expectation, so gnomAD's model fits this gene poorly and the ratio says little. Missense variants: 1,165 observed, 1,111.9 expected, observed/expected ratio (o/e) 1.05, 90% interval 1 to 1.1. Synonymous variants: 663 observed, 519.39 expected, observed/expected ratio (o/e) 1.28, 90% interval 1.2 to 1.36.
Homologues: Orthologues: chimpanzee FAAP100 (99% identical), macaque FAAP100 (98% identical), guinea pig FAAP100 (76% identical), pig FAAP100 (74% identical), mouse Faap100 (73% identical), rat Faap100 (73% identical), dog FAAP100 (71% identical), tropical clawed frog faap100 (28% identical), zebrafish faap100 (27% identical).
Diseases named in the same sentence as FAAP100 in open-access papers:
FAAP100 is named in the same sentence as 14 diseases in open-access papers, as found by Europe PMC text mining. Sharing a sentence is not in itself a finding about the gene and the disease. The quoted sentences say what the papers report.
Fanconi anemia (9 papers, 2011 to 2025). Fanconi anemia (FA) is a hereditary DNA repair disorder characterized by progressive pancytopenia with bone marrow failure, variable congenital malformations and predisposition to develop hematological or solid tumors. "The authors identify FAAP100 gene variants as causing a severe subtype of Fanconi anemia characterized by multi-organ developmental abnormalities and bone marrow deficiency at birth." (PMID 40244696, 2025). "The protein encoded by FAAP100 regulates FANCD2 monoubiquitination and the stability of the Fanconi anemia core complex, playing a role in the Fanconi anemia-associated DNA damage response." (PMID 37372448, 2023). "FAAP100 is involved in the Fanconi anemia (FA) core complex, which plays a role in the DNA damage response network." (PMID 22206413, 2011). "Faap100 protein regulates Fancd2 monoubiquitination and the stability of the Fanconi anemia core complex, which could significantly affect the DNA damage response associated with Fanconi anemia." (PMID 38338077, 2024). "Another two genes (EME2 and FAAP100) were significantly enriched in the Fanconi anemia pathway." (PMID 37372448, 2023).
breast carcinoma (3 papers, 2015 to 2024). "Among breast cancer subtypes, the top eight mutational rates were MAD2L2/FANCV (37.5%), FANCI (32%), ATR (32%), FAAP20 (30%), FAAP100 (28%), SLX4 (27%), FANCT (27%), and BRIP1 (26%) in breast invasive carcinoma NOS." (PMID 39421870, 2024). "Germline mutations in DNA mismatch repair genes (BRCA1, BRCA2, CHEK2, ERCC4, FAAP100, and TP53BP1, amongst others) are associated with breast cancer susceptibility." (PMID 27608040, 2016).
anemia (2 papers, 2011 to 2025). A reduction in the number of red blood cells, the amount of hemoglobin, and/or the volume of packed red blood cells. "In mice 2310003H01Rik is the predicted ortholog of FAAP100, Fanconi anemia-associated protein, 100 kDa." (PMID 22206413, 2011).
Anophthalmia (1 paper, 2025). Absence of the globe or eyeball. "Anophthalmia, hydrocephalus, and limb malformations were observed in 6 of 62 Faap100–/– and Faap100+/– mice." (PMID 40232843, 2025).
Atrophy (1 paper, 2025). Any weakening or degeneration, especially through lack of use. "In a confirmatory animal model, customized Faap100–/– mice exhibited embryonic lethality, microsomia, malformations, and gonadal atrophy resembling mice with established FA subtypes." (PMID 40232843, 2025).
bone marrow failure (1 paper, 2025). "Pancytopenia or bone marrow failure, as assessed by peripheral blood counts, was not present in Faap100–/– mice in a 6-month pilot study." (PMID 40232843, 2025).
hypogonadism (1 paper, 2023). A disorder characterized by decreased function of the gonads. "In the present study, we found that Faap100−/− mice shared a hypogonadism phenotype with FA-null mouse models." (PMID 37580696, 2023). "In this study, we first constructed Faap100 knockout mouse model and found Faap100−/− mice had hypogonadism with a dramatic reduction of PGCs from E9.5, a time before entering into meiosis for both male and female germ cells." (PMID 37580696, 2023).
Infertility (1 paper, 2025). "Consistently, the prominent feature of the present Faap100–/– mouse model was gonadal atrophy with corresponding infertility." (PMID 40232843, 2025).
Premature ovarian insufficiency (1 paper, 2023). Amenorrhea due to loss of ovarian function before the age of 40. "In addition, Faap100−/− females displayed high levels of serum follicle-stimulating hormone (FSH) and the disappearance of estrous cycles, indicating that Faap100−/− females phenocopied human premature ovarian insufficiency (POI)." (PMID 37580696, 2023).
neoplasia (2 papers, 2023 to 2025). "The observation period in our study was too short to systematically evaluate the Faap100–/– mouse model in terms of bone marrow failure (BMF) or neoplasia." (PMID 40232843, 2025).
cancer (1 paper, 2025). A tumor composed of atypical neoplastic, often pleomorphic cells that invade other tissues. "FAAP100 can now become an integral part of mutation screens for FA and should be considered for mutation assessment in breast and other cancers." (PMID 40232843, 2025).
FAAP100 also shares sentences with these, for which no sentence is quoted: Hydrocephalus (1 paper); invasive carcinoma (1); Pancytopenia (1).